RAC1 (Rac family small GTPase 1)
Diseases named in the same sentence as RAC1 in open-access papers (continued):
Sharing a sentence is not in itself a finding about the gene and the disease.
cervical carcinoma (continued). "We further examined the generality of our findings, by examination of migration rate and Rac1 activity in the cervical cancer cell line SiHa." (PMID 18253510, 2008). "Notably, Rac1-mediated p38 activation in response to γ-rays supported cervical carcinoma cell survival, and the inhibition of Rac1 activity abrogated the radioresistance conferred by Rac1/p38 activation and significantly enhanced apoptosis." (PMID 36732057, 2023). "In addition, HPV18 E6 activates the small GTPase Rac1 and subsequently contributes to the E6 stimulation of NFκB in cervical cancer." (PMID 36077689, 2022). "Under experimental conditions on HeLa cells, the authors found that a phytochemical quercetin decreased Rac1 expression, which could be useful in reduction of cervical cancer metastasis." (PMID 32443784, 2020). "Moreover, both HPV-negative and HPV-positive cervical cancer derived cells have nuclear staining for Rac1." (PMID 22443139, 2012). "Activation of the Wnt signaling pathway plays an important role during cervical cancer progression; therefore nuclear Rac1 may cooperate with this pathway to stimulate proliferation of cervical cancer cells." (PMID 22443139, 2012). "We monitored reduced Rac1-dependent migration also in the cervical cancer cell line SiHa." (PMID 18253510, 2008). "E3 ligase MARCH 7 acts as a tumor-promoting gene in human cervix cancer via interacting with VAV2, triggering the activation of CDC42 and RAC1, i.e., VAV1/RAC1/CDC42 pathway." (PMID 34769401, 2021). "Rac1 inhibitor NSC23766 inhibited Rac1 activation by Rac-specific GEFs Trio or Tiam1 in ovarian and cervical cancer." (PMID 32443784, 2020). "Metformin displays antimigration effects in cervical cancer cells by inhibiting filopodia and lamellipodia formation through the suppression of FAK, Akt and its downstream Rac1 and RhoA protein." (PMID 31870092, 2019). "Moreover, it has been shown that in the cisplatin-resistant cervical cancer tumors, expression of SH3BP1, Rac1 and WAVE2 mRNA is significantly upregulated compared to cisplatin-sensitive cancer tissues." (PMID 34572403, 2021). "Consistently, nuclear Rac1 was observed in the cervical cancer cell lines C33A and SiHa, but not in non-tumorigenic cells, such as HaCat, suggesting a role of nuclear Rac1 in disease progression." (PMID 27442895, 2017). "We found that chemical inhibition of Rac1 reduces the proliferation of cervical cancer cell lines C33A and SiHa, as well as that of non-tumorigenic HaCat cells." (PMID 22443139, 2012). "RAC1 and CDC42 may involve in the progression of cervical cancer migration as downstream of HMGB1." (PMID 30962261, 2019). "RAC1 and CDC42 may be involved in the progression of cervical cancer migration induced by HMGB1." (PMID 30962261, 2019). "We have previously shown colocalization of ezrin in adherens junctions with N-Cadherin but no expression of E-Cadherin in HPV 18 containing HeLa cervical carcinoma cells, as well as the requirement for Rac1, phosphatidylinositol-4-phosphate 5-kinase (PIPKα) and RhoA for this localization." (PMID 21747943, 2011). "Therefore, it is possible that inhibition of the cytoplasmic pool of Rac1 in both cervical cancer-derived and non-tumorigenic cells may result in a reduction of cell proliferation, independently of Rac1 nuclear functions." (PMID 22443139, 2012).
lung adenocarcinoma (33 papers, 2009 to 2025). A carcinoma that arises from the lung and is characterized by the presence of malignant glandular epithelial cells. "CBX3 overexpression has been linked to the advancement of lung adenocarcinoma via activation of the RAC1 pathway, a component of the Wnt signaling network." (PMID 39272883, 2024). "Rather, lung adenocarcinomas have been reported to up-regulate a spliced variant of RAC1 with a 19-amino acid in-frame insertion known as Rac1b, particularly in tumors from smokers and patients who showed node positive disease." (PMID 32158759, 2020). "Moreover, Rac1, alongside p130Cas, was determined to be pivotal in the carcinogenic mechanisms underlying lung adenocarcinoma." (PMID 40362257, 2025). "Hence, this suggested that the inhibition of lung adenocarcinoma cell motility in StarD13-depleted cells could be through the indirect inhibition of Rac1, caused by the constitutive activation of RhoA." (PMID 32900380, 2020). "The collaboration between Rac1 and p130Cas was instrumental in enhancing cell proliferation and provided resistance to anoikis in lung adenocarcinoma cells." (PMID 40362257, 2025). "Rac1, working in tandem with p130Cas, was found to be a key player in the carcinogenesis of lung adenocarcinoma." (PMID 40362257, 2025). "Rac1, in conjunction with p130Cas, was identified as a significant contributor to the carcinogenic processes in lung adenocarcinoma." (PMID 40362257, 2025). "This collaboration between Rac1 and p130Cas was crucial for the induction of invasion in lung adenocarcinoma cells." (PMID 40362257, 2025). "According to the findings, lung squamous cell carcinoma and lung adenocarcinoma cells have higher levels of RAC1, RPN1, and SLC7A11 mRNA than normal lung epithelial cells." (PMID 38968580, 2024). "Evidence suggests that smoking-associated upregulation of CBX3 can accelerate the progression of lung adenocarcinoma (LUAD) by activating the ARHGAP24/Rac1 signaling axis." (PMID 39272883, 2024). "The candidate proteins GAPDH and RAC1 showed the highest connectivity with other differentially expressed proteins between the lung adenocarcinoma group and the healthy group using STRING." (PMID 36404333, 2022). "Rac1 is activated by nectin‐4, and in human lung adenocarcinoma, the expression of nectin‐4 activates Rac1 and promotes tumour cell invasion and growth." (PMID 35905293, 2022). "The ToppFun FEA, relative to diseases, predicted a possible association of the RAC1, CFH and 5 of the 14-3-3 protein family genes, namely SFN, YWHAB, YWHAE, YWHAG and YWHAZ with lung adenocarcinoma." (PMID 35366267, 2021). "In tumor tissue from patients with lung adenocarcinoma and lung squamous cell carcinoma, RAC1 was over expressed, compared to normal tissue." (PMID 35366267, 2021). "Lastly, analysis of databases revealed amplification of the RAC1 gene in lung adenocarcinomas, ranging from 3 to 5.5% depending on the database." (PMID 32158759, 2020). "Here, we demonstrated that Crk induced EMT in A549 human lung adenocarcinoma cells through differential regulation of Rac1/Snail and RhoA/Slug, leading to decreased expression of E-cadherin and increased N-cadherin, fibronectin, and MMP2 expression." (PMID 27027347, 2016). "Next, we examined the effect of Rac1 knockdown on tumorigenesis and metastatic behavior of lung adenocarcinoma cells." (PMID 21347385, 2011). "Significantly, the sphere formation capability was also compromised upon Rac1 knockdown (lung adenocarcinoma sample #1) or NSC23766 treatment in two different lung adenocarcinoma samples (lung adenocarcinoma sample #2)." (PMID 21347385, 2011). "Together, Rac1 and p130Cas facilitated migration in lung adenocarcinoma cells." (PMID 40362257, 2025). "Additionally, the protein Rac1, in partnership with p130Cas, was recognized as playing a crucial role in the development of lung adenocarcinoma." (PMID 40362257, 2025).
lung adenocarcinoma (continued). "TGFβ1 signaling to PI3Kγ/AKT/RAC1 or through RAC1/ROS mediates cell migration of hepatic stellate cells in liver fibrosis or invasiveness of PDAC cells, respectively, whereas TGFβ/Smad3 signaling through DOCK4 and RAC1 facilitates lung adenocarcinoma metastasis." (PMID 33266416, 2020). "Therefore we sought to elucidate the mechanism through which the StarD13/RhoA/Rac1 pathway regulates cell migration in lung adenocarcinoma cells, by examining its effects on cell adhesion dynamics." (PMID 32900380, 2020). "In work carried out on a panel of lung adenocarcinoma cell lines we found that ectopic RAC1B expression was associated with increased E-cadherin and decreased Vimentin expression and in contrast to RAC1 was unable to induce EMT and invasive activity in an in vivo chorioallantoic invasion model." (PMID 31817229, 2019). "In addition, the induction of EMT in A549 human lung adenocarcinoma cells by Crk was mediated through the distinct regulation of the Rac1/Snail and RhoA/Slug signaling pathways, which led to a decrease in E-cadherin expression alongside increased levels of N-cadherin, fibronectin, and MMP2." (PMID 40362257, 2025). "Furthermore, there was no somatic mutation detected in RAC1 in lung adenocarcinomas from TCGA cohort, whereas increased copy number was observed at the RAC1 locus in lung adenocarcinomas." (PMID 31779616, 2019). "Moreover, a pro-metastatic role for DOCK4, which is induced by TGF-β in lung adenocarcinoma cells, unveiled an unexpected link between EMT, Rac1 activation, and metastatic dissemination." (PMID 32158759, 2020). "For example, A549 lung adenocarcinoma cells and ECV304 endothelial-derived cells adhering to laminin-10/11 show more robust Rac1 activation compared to these same cells on vitronectin, and further dominant negative Crk proteins that don't interact with DOCK1 block Rac1 activation." (PMID 19426560, 2009). "Whether BCR downregulation leads to Rac1 activation in lung adenocarcinoma has not yet been investigated." (PMID 38612674, 2024).
neuroblastoma (31 papers, 2011 to 2025). Neuroblastoma (NB) is the most common solid, extracranial childhood tumor. "Pneumolysin has also been reported to cause activation of RhoA and Rac1 GTPases in neuroblastoma cells at sublytic concentrations." (PMID 23527286, 2013). "Interestingly, recurrent somatic oncogenic driver mutations of Rac1 have been identified in 5%–9% of tumor DNA from patients with melanoma which similar to neuroblastoma also originates from cells within the neural crest." (PMID 30760980, 2019). "Methamphetamine causes cytotoxicity by inducing macropinocytosis through the activation of Ras and Rac1 and lysosomal dysfunction in human neuroblastoma cells." (PMID 39906392, 2024). "Elegant data from DeGeer and colleagues showed that blocking tyrosine phosphorylation of specific residues within the C-terminus of Trio prevented netrin-induced Rac1 activation in N1E–115 neuroblastoma cells." (PMID 37528624, 2023). "In human neuroblastoma cells, Rac1 was found to indirectly increase Tau phosphorylation via translocation of SET, a protein phosphatase 2A (PP2A) inhibitor." (PMID 36779014, 2023). "Overexpression of phospholipid phosphatase-related protein 1 (PLPPR1) in the mouse neuroblastoma cell line (Neuro2a) reduces the level of active Rac1." (PMID 34079763, 2021). "Surprisingly, as opposed to its well reported repulsive role, overexpression of Unc5a in N1E-115 neuroblastoma cells has been shown to induce neurite outgrowth by increasing Rac1 and Cdc42 activity." (PMID 30934641, 2019). "In neuroblastoma N1E-115 cells, Rac1 and Rac3 appear to play opposite roles, since depletion of Rac1 leads to decreased focal adhesions and cell rounding, while depletion of Rac3 induces stronger adhesions and growth of neurite-like protrusions." (PMID 31514269, 2019). "Work in fibroblasts, rat commissural neurons, and N1E-115 neuroblastoma cells showed that netrin-1/DCC signaling increases Rac1 and Cdc42 activities, while decreasing RhoA activity." (PMID 30934641, 2019). "We then used a human neuroblastoma cells (M17) stably over-expressing alpha-synuclein and found that RAC1 function decreased the amount of amyloidogenic alpha-synuclein." (PMID 29429047, 2018). "Addition of Aβ to human neuroblastoma cells resulted in reduced neurite length concomitant with enhanced activation of RhoA and diminished activation of Rac1." (PMID 25339865, 2014). "Here, we demonstrate that the full length of the mouse FRMD7, rather than the N-terminus or the C-terminus alone, directly interacts with RhoGDIα and specifically initiates Rac1 signaling in mouse neuroblastoma cell line (neuro-2a)." (PMID 23967341, 2013). "Moreover, Aβ treatment on human neuroblastoma cells led to an increase in RhoA activation and a decrease in Rac1 activation." (PMID 39050707, 2024). "We next sought to determine whether Rac1-induced Rho activation was unique to Neuro-2a neuroblastoma cells." (PMID 38102112, 2023). "For example, the expression of constitutively active Rac1 leads to neurite outgrowth through the generation of filopodia and lamellipodia in the developing growth cone, and dominant negative Rac1 inhibits these effects in N1E-115 neuroblastoma cells." (PMID 33081375, 2020). "As Rho signaling is highly activated during the initiation and migration of neural crest cells, deregulated Rho/Rac1 signaling could represent an oncogenic hit during neuroblastoma development." (PMID 30760980, 2019). "Moreover, it has also been reported that Unc5a-overexpressing N1E-115 neuroblastoma cells lead to transient Rac1 activation in early stages and RhoA activation in the later stages of neurite outgrowth." (PMID 30934641, 2019). "Interestingly, extracellular oligomeric α-SYN impairs RAC1 activity in neuroblastoma cells." (PMID 29429047, 2018). "As proof, in human neuroblastoma SH-SY5Y cells, methamphetamine (METH)-induced macropinocytosis was highly related to the activation of Rac1." (PMID 36765917, 2023).
neuroblastoma (continued). "Similarly, the activation of Rac1 observed after AUTS2 overexpression in N1E-115 mouse neuroblastoma cells (the “AUTS2-Rac1 pathway”) may also be explained, at least in part, by AUTS2 regulation of transcripts Prex1 and Rasgrf2, which were significantly reduced in Auts2del15/del15 neocortex." (PMID 35431798, 2022). "Activation of Rac1 was observed following stimulation with serotonin in Chinese hamster ovary (CHO) cells, mouse primary neurons, and in the human IMR32 neuroblastoma cell line." (PMID 29246246, 2017). "Neuroblastoma cells were incubated with JNK inhibitor (SP600125; 20 μM) with metformin (10 mM) in presence of Rac1 inhibitor (NSC23766; 25 μM) or Cdc42 inhibitor (ML141; 10 μM), and cell viability was measured." (PMID 25365944, 2014). "We showed that paxillin phosphorylation, acting through the Rac1/Cdc42/cJNK signaling cascade, is activated following neurite extension in mouse N1E115 neuroblastoma cells." (PMID 23626709, 2013). "We expressed each MAP1B construct (FL, HC, and LC1) in neuroblastoma N1E115 cells, and measured the activity of Rac1." (PMID 23300879, 2012). "In SH-SY5Y neuroblastoma models, we show that ANKK1 interacts with the synapse protein FERM ARH/RhoGEF and Pleckstrin Domain 1 (FARP1), which is a guanine nucleotide exchange factor (GEF) of the RhoGTPases RAC1 and RhoA." (PMID 39409035, 2024). "Indeed, TENM4 KO neuroblastoma cells of mouse origin display decreased neurite length and ability to generate filopodia-like protrusions through FAK, Cdc42 and Rac1, whereas TENM4 overexpression in neuroblastoma cells promotes protrusion formation." (PMID 33652578, 2021). "By expressing constitutively active or dominant negative forms of Rho GTPases, and by using specific inhibitors of Rac1, Cdc42, and JNK, we further confirmed the role of impairments in Rho GTPase signaling in mediating metformin effects on the survival of neuroblastoma cells." (PMID 25365944, 2014). "Thus, the JNK phosphorylation of paxillin, possibly after Rac1/Cdc42 signaling cascade stimulation, plays a critical role in neurite extension in mouse N1E115 neuroblastoma cells." (PMID 23626709, 2013). "However, reduced rather than increased levels of activated Rac1 (Rac1GTP) were found in cell lysates of SH-SY5Y neuroblastoma cells overexpressing SOD1 mutants G93A and H80R." (PMID 30214670, 2018). "The results obtained in neuroblastoma cells support that endogenous MAP1B heavy and light chain 1, can assemble a protein complex with expressed myc-HC and myc-LC1 construct, making not possible to distinguish the real contribution for each fragment toward Rac1 activity." (PMID 23300879, 2012). "In addition, the lack of observed Rac1 and Rac3 binding seen in the present study may reflect minimal regulation of these Racs by P-Rex1 relative to the overall Rac1 or 3 activity levels within neuroblastoma cells and warrants further investigation." (PMID 38884093, 2024).